MAOA (monoamine oxidase A)
Diseases named in the same sentence as MAOA in open-access papers (continued):
Sharing a sentence is not in itself a finding about the gene and the disease.
cancer (continued). "In PC, several studies revealed a potential role for MAOA in mediating prostate tumorigenesis and cancer metastasis." (PMID 37403079, 2023). "MAOA has been consistently found to be highly expressed in PC and to promote cancer growth, progression and metastasis." (PMID 36860320, 2023). "A growing body of evidence indicates that MAOA either has altered expression levels or exerts a regulatory effect in a variety of types of cancer." (PMID 36860320, 2023). "MAOA promotes PC metastasis not only by promoting EMT in cancer cells per se but also by modifying the tumor microenvironment." (PMID 36860320, 2023). "After considerable interest and effort focused on understanding the role of MAOA in the brain, recent studies have started to reveal the importance of MAOA in cancer." (PMID 36860320, 2023). "The Spearman correlation coefficient (ρ) was 0.822 between the mRNAs of MAOA and MAOB in the same cancer tissues, indicating a significant positive association (p < 0.001)." (PMID 34209963, 2021). "MAOA is overexpressed in prostate tumors, and it promotes cancer cell proliferation, stemness, and tumorigenesis." (PMID 33763378, 2021). "Significantly strong positive associations were also found between the mRNAs of MAOA, MAOB, and COMT in the same cancer tissues." (PMID 34209963, 2021). "The open database of cancer gene expression was examined for the expression of MAOA in gene expression omnibus (GEO) profile datasets (GDS1650 and GDS3321)." (PMID 33763378, 2021). "MAOA expression in cancer tissues was analyzed by immunohistochemistry and was compared with the patient SUVmax value of PET-CT and other clinicopathological characteristics." (PMID 33855088, 2021). "For example, downregulation of MAOA was found in several cancers, including malignant melanomas, breast cancer, and cholangiocarcinomas." (PMID 32316576, 2020). "The outcome exhibited in the MAOA expression levels in patients with HCC was significantly lower than that in the non‐cancer groups (SMD = −0.32, 95% CI: −0.45 to −0.18)." (PMID 32931665, 2020). "Recently, accumulating evidence has demonstrated that MAOA plays an important role in cancer progression 15, 18-22." (PMID 32792865, 2020). "Conversely, MAOA was downregulated in a number of cancer tissues and significantly differed between them." (PMID 31467634, 2019). "Curcumin was discovered to inhibit cancer-associated fibroblast (CAF)-induced EMT and invasion in PC3 cells by suppressing the monoamine oxidase A (MAOA)/mTOR/HIF-1α signaling pathway." (PMID 30200668, 2018). "MAOA has been demonstrated to promote prostate tumorigenesis and cancer metastasis, and this study revealed that WCE inhibited MAOA expression, a promising therapeutic effect." (PMID 29066975, 2017). "The most investigated genes were those implicated in neuroendocrine stress responses; dopamine, norepinephrine, and serotonin signalling; apoptosis; insulin secretion; neuroplasticity; reproduction; foetal growth; and cancer (e.g. MAOA, BRSK2, ADCYAP1, BDNF, DRD2, IGF2, H19)." (PMID 41070359, 2025). "In addition, monoamine oxidase A, an important enzyme in the metabolism of monoamines, could lead to T cell dysfunction, which reduces the cancer immunotherapy efficacy of immune checkpoint therapy and is strongly associated with lower survival of various cancers." (PMID 38783893, 2024). "Preclinical studies have suggested that monoamine oxidase A (MAO-A) inhibitors and SSRIs may influence the tumor microenvironment exerting a synergistic cytotoxic effect with anti-PD-1 therapy on cancer cells." (PMID 39664396, 2024). "Furthermore, MAOA up-regulation occurs not only in cancer cells but also in stromal cells, tumor-infiltrating T cells, and tumor-associated macrophages." (PMID 39010072, 2024).
cancer (continued). "One of MAOA’s key functions is to induce EMT by producing excessive intracellular levels of hydrogen peroxide, a major reactive oxygen species by-product generated by MAOA-mediated enzymatic reactions, in which cancer cell aggressiveness, invasiveness, and metastatic potential are increased." (PMID 37403079, 2023). "To further demonstrate whether MAOA is correlated to ferroptosis in cancer samples, we detected the correlation of MAOA with ferroptosis by immunohistochemistry (IHC) staining of MAOA and 4‐HNE in human kidney renal clear cell carcinoma samples." (PMID 36627132, 2023). "Cancer-cell-derived MAOA also enables cancer-stromal cell interaction involving bone stromal cells and nerve cells by secretion of Hedgehog and class 3 semaphorin molecules respectively to modulate the tumor microenvironment in favor of invasion and metastasis." (PMID 36860320, 2023). "In contrast, the MAOA expression decreases with the development of cancer." (PMID 36902343, 2023). "AR, MIF, HSP90B1, and MAOA were expressed in more than 50% of cancer cells with high expression levels and may have potential therapeutic targets." (PMID 36452480, 2022). "Additionally, we showed that MAOA abrogates cancer cell growth and serves as an independent biomarker for LUAD." (PMID 33763378, 2021). "Indeed, in various types of human cancers, a previous report demonstrated the downregulation of MAOA." (PMID 34209963, 2021). "In addition, in OECM-1 and HSC-3 cancer cells, compared to the control group, downregulation of MAOA mRNA and protein was found to be statistically significant after arecoline treatment (p < 0.05)." (PMID 34209963, 2021). "Depending on the cancer type, MAOA can either have a tumour-promoting or tumour-suppressive role." (PMID 32273550, 2020). "Conversely, other studies have found a downregulation trend of MAOA in several cancers." (PMID 32931665, 2020). "Moreover, several studies suggested that MAOA can promote cancer progression through induction of EMT." (PMID 31467634, 2019). "These limited studies on the role of MAOA in cancer metastasis are controversial." (PMID 29334991, 2018). "The functional implications and mechanisms of reduced MAOA expression in cancer cells are unclear." (PMID 25978500, 2015). "Moreover, MAOA is not only expressed in PCa cells but also in other types of epithelial cells, stromal cells, intratumoral T cells, and TAMs, which collectively enhance cancer progression and metastasis." (PMID 38349393, 2024). "The MAOA rs5953210 polymorphism was significantly associated with severe BUD (odds ratio, 6.43; 95% confidence interval, 5.12–7.74; p < 0.01) and might contribute to BQ-associated cancer risk." (PMID 38392182, 2024). "In addition to nurturing blood-borne metastasis, we recently showed that MAOA also promotes perineural invasion, a nerve-facilitating route of PC metastasis, in a 3-dimensional cancer-nerve cell co-culture model, and tumor innervation in an orthotopic xenograft model." (PMID 36860320, 2023). "Previously, we showed MAOA activity is inhibited by NMI and inhibited cell growth in various cancer cell cultures." (PMID 39904854, 2025). "These constitute a MAOA-directed interplay between oxidative stress, hypoxia, EMT and tumor-stromal interaction to cooperatively promote cancer cell aggressiveness and invasiveness." (PMID 36860320, 2023). "Correlation analysis also shows that the following histaminergic transcripts: GNA15, HRH2, MAOA, WASF2, and those related to inflammation: AEBP1, CXCL1, 2, 3, and 8, SPHK1, and TNFAIP6 play an important role in cancer tissue." (PMID 36902343, 2023). "Monoamine oxidase A (MAOA) is a mitochondrial enzyme that is involved in prostate tumorigenesis and cancer metastasis." (PMID 37403079, 2023). "Taking into consideration the cancer development process, the following histaminergic genes stood out: GNA15, HRH1-HRH4, MAOA, WASF2, along with inflammation-related genes: AEBP1, CXCL1, CXCL2, CXCL3, CXCL8, SPHK1, and TNFAIP6." (PMID 36902343, 2023).
cancer (continued). "Several reagents, such as monoamine oxidase A (MAO-A) inhibitors, proteasome inhibitors, and regorafenib, have been shown to improve cancer immunotherapy by reprogramming TAMs." (PMID 36359867, 2022). "Monoamine oxidase A (MAOA), the enzyme isoform specific for serotonin degradation, is however also down-regulated ín 17/28 cancers and is only significantly up-regulated in kidney renal clear cell carcinoma." (PMID 36286592, 2022). "MAOA is overexpressed in NSCLC and stimulates the epithelial–mesenchymal transition in cancer cells." (PMID 33763378, 2021). "Tissue expression was confirmed to be significantly different in cancer vs. control samples for DNA2, MAOA, PARP1, TYR, and HDAC1 in the IST Online database and for PTK2B, MAOA, PARP1, and TYR in the GEPIA2 database." (PMID 34199192, 2021). "In murine and human cells, 5-HIAAld is formed from serotonin by monoamine oxidase A (MAO-A), a catecholamine-metabolizing enzyme that is downregulated in human and animal cancer tissues." (PMID 32429145, 2020). "Recently, several studies have discussed the expression levels of monoamine oxidase (MOA) A (MAOA) and MAOB in cancers; however, controversial characteristics were identified for these two enzymes." (PMID 32316576, 2020). "A growing body of evidence has demonstrated that MAOA plays a role in the progression of various cancers including NSCLC, and the expression of MAOA in various cancers is different 15, 18-22." (PMID 32792865, 2020). "The expression levels of MAOA in the HCC patients and non‐cancer groups were compared using the mean (M) expression levels and standard deviation (SD)." (PMID 32931665, 2020). "The top IPA network constructed from member proteins was associated with cell-to-cell signalling and interaction, small molecule biochemistry and cancer, where both SENENBP1 and MAOA were upregulated." (PMID 32616892, 2020). "The MAOA gene is highly expressed in tumor-infiltrating, exhausted CD8 T-cells, especially those with elevated PD-1, Tim-3, and LAG-3 levels, making them less effective at fighting cancer." (PMID 40298832, 2025). "Further investigation of ALDH1A1, MAOA, and particularly KLF4 in a patient cohort is warranted, and their involvement in maintaining cancer stem cell populations could lead to novel areas of investigation for non-surgical treatment of EEC and LNG resistance." (PMID 38635728, 2024). "In non-small-cell lung cancer (NSCLC), the expression of protein and mRNA levels of MAOA were higher in cancer tissues than those observed in adjacent non-cancerous tissues." (PMID 34209963, 2021). "MAOA inhibitors are used effectively in the treatment of various neuropsychiatric disorders, but since neurotransmitters are the preferred substrates of MAOA, non-targeted delivery of MAOA for the treatment of cancers would be detrimental." (PMID 34141613, 2021). "Monoamine oxidases A and B (MAOA and MAOB) are highly expressed in many cancers." (PMID 26689994, 2016). "Mechanistically, MAOA in stromal cells enhances IL-6 transcription and expression through Twist1 binding to an E-box element on the IL-6 promoter, which in turn activates paracrine IL-6/STAT3 signaling to transcriptionally upregulate the cancer stem cell marker CD44 in adjacent PC cells." (PMID 36860320, 2023). "Moreover, enzymes such as monoamine oxidase A (MAOA) degrading catecholamines and serotonin may also play an important role in influencing cancer metastasis." (PMID 29334991, 2018). "While there is no explanation for the double-edged role of MAOA in different cancer types so far, we speculate that different cell context or cell type-specific gene expression in different types of cancer cells may have an influence on the tumor suppressor or oncoprotein activities of MAOA." (PMID 34209963, 2021). "Because of our limited sample size, we performed Fischer’s exact tests and found that only the MAOA rs5953210 GG SNP was significant; the other SNPs related to BUD and cancers were not correlated with addiction." (PMID 38392182, 2024).
tumor (81 papers, 2008 to 2026). "They reported last year on their investigation of the potential of monoamine oxidase A for reprogramming tumor-associated macrophages." (PMID 36650218, 2023). "In previous studies, MAOA expression in tumor cells was associated with poor prognosis in several tumors." (PMID 37509535, 2023). "Several studies have reported high levels of MAOA transcripts in malignant prostate epithelium and associated them with higher Gleason grades and tumor severity." (PMID 32630240, 2020). "Taken together, our data provide evidence of a tumour-suppressive function for MAOA in EBV-associated NPC." (PMID 32273550, 2020). "Notably, in male patients, genetic variation in MAOA was significantly associated with serotonin levels in tumour tissue and five SNVs were identified as potential contributors to this association." (PMID 41152544, 2025). "MAOA can directly influence the expression of immunosuppressive molecules (immune checkpoints) on immune cells (to subsequently regulate immune cell activation) or regulate the tumor microenvironment (TME) by affecting tumor-associated immune cell metabolites." (PMID 38349393, 2024). "Taken together, our data point to a central role for EBV in mediating the tumour suppressive effects of MAOA and that loss of MAOA could be an important step in the pathogenesis of NPC." (PMID 32273550, 2020). "Similarly, MAOA plays key roles in regulating neurodegeneration, neuron death, and neuron activity in neuronal synapses and affects T cell reactivity through “immune synapses” via immunosuppressive tumor-associated macrophages (TAMs) and tumor growth." (PMID 38349393, 2024). "This study shows protein interactions with NMI, a chemical conjugate of MAOA inhibitor clorgyline and tumor-seeking dye, MHI-148." (PMID 39904854, 2025). "Two MAOA peptides were detected by LC–MS/MS in the 65 kD band of NMI treated MC-38 tumor tissues: [K].WVDVGGAYVGPTQNR.[I]; [K].INVLVLEAR.[D]]." (PMID 39904854, 2025). "Our study shows NMI binds to albumin but highly prefers MAOA, providing a plausible mechanism for systemic drug delivery via serum albumin to the tumor target and subsequent MAOA inhibition." (PMID 39904854, 2025). "Decreased JARID1D expression in tumor cells correlated with reduced AR activity, increased MAOA levels, and elevated RANKL secretion." (PMID 39816691, 2025). "It is noted that bioinformatics analysis showed that, holistically, MAOA expression was negatively correlated with CD8+ T cell immune infiltration in most tumor types, however, there were also some tumor types that showed a positive correlation." (PMID 38349393, 2024). "Previous findings showed that MAOA was expressed as a key molecule in tumor-infiltrating T cells (TILs), resulting in T cell dysfunction." (PMID 38349393, 2024). "MAOA knockout (KO) mice exhibited significant tumor growth inhibition in two homozygous mouse tumor models." (PMID 38349393, 2024). "Blocking receptors like muscarinic receptor 3 (M3R) and monoamine oxidase A (MAOA) have shown decreased tumor growth and altered immune responses in CRC models." (PMID 39199569, 2024). "This improved tumor-suppressive response was accompanied by increased release of the cytokine IL-2 and the cytotoxic molecule interferon-gamma in MAOA KO mice, suggesting that knocking out MAOA led to increased CD8+ T cell activity." (PMID 38349393, 2024). "In this review, we retrospect that MAOA inhibits the activities of various types of tumor-associated immune cells (such as CD8+ T cells and tumor-associated macrophages) by regulating their intracellular monoamines and metabolites." (PMID 38349393, 2024). "That is, the MAOA gene was highly expressed in the most “exhausted” tumor-infiltrating CD8+ T cells (PD-1hiTim-3hiLAG-3hi)." (PMID 38349393, 2024). "Tumor-derived MAOA stimulates osteoclastogenesis, tipping the balance towards bone destruction and creating a pre-metastatic niche for initiating bone metastasis." (PMID 36860320, 2023).
tumor (continued). "MAOA also possesses a unique advantage as a therapeutic target given its dual targeting potential in both the tumor and stromal components to effectively block tumor progression." (PMID 36860320, 2023). "The expressions of ALDH3A2 and MAOA were significantly lower in STAD tumor tissues than those in the paired adjacent normal tissues, respectively (all P < 0.05)." (PMID 36915111, 2023). "Collectively, these studies demonstrate that MAOA of tumor or stromal cell origins dictates tumor-stromal cell interactions to favor reprogramming of naïve stroma towards a tumor-supportive phenotype." (PMID 36860320, 2023). "Taken together, these data demonstrate that MAOA inhibits tumor growth via suppressing the protective effect of 5‐HT, implying a potential role of MAOA as a tumor suppresser via ferroptosis." (PMID 36627132, 2023). "Conversely, knockdown of MAOA or pharmacological inhibition of MAOA delayed the onset of metastasis, reduced tumor burden in bone and visceral organs, and prolonged mouse survival compared to controls." (PMID 36860320, 2023). "Research has shown that MAOA promotes tumor invasion, migration, and epithelial–mesenchymal transition." (PMID 36936412, 2023). "Higher expressions of NOX4 and FKBP10, and lower expressions of ALDH3A2 and MAOA were observed in tumor samples compared with the normal tissues, respectively." (PMID 36915111, 2023). "Analyses of both public data and our data reveal that the expression of MAOA is downregulated in LUAD compared with non-tumor tissue." (PMID 33763378, 2021). "Recently, tumor-derived monoamine oxidase A (MAOA) was also shown to stimulate osteoclastogenesis by promoting osteoblast-derived receptor activator nuclear kappa B ligand (RANKL) and IL6 expression." (PMID 34803925, 2021). "The results showed that the MAOA mRNA level of LUAD tumor in both human (GDS1650) and mice (GDS3321) was significantly lower than the normal tissue." (PMID 33763378, 2021). "The MAOA or MAOB expression levels in tumor tissue were closely correlated with the patient SUV max values of PET-CT and immunotherapy evaluation indices, such as PD-L1 and the microsatellite status." (PMID 33855088, 2021). "The IHC staining showed that the MAOA expression was reduced in LUAD specimens compared with non-tumor controls, which was inconsistent with the mRNA results." (PMID 33763378, 2021). "Clinical and in vitro data indicate that MAOA functions as a tumor suppressor in hepatocellular carcinoma, cholangiocarcinoma, pheochromocytoma, neuroblastoma, renal cell carcinoma, and oral and pharyngeal cancers." (PMID 33763378, 2021). "Our results consistently indicate a significant downregulation of MAOA in tumor tissues compared to adjacent non-tumor tissues." (PMID 34209963, 2021). "We also noted that the expression of MAOA in HK1 cells (derived from a well-differentiated EBV-negative NPC tumour) was comparable to that of the NP460hTert cells, and its levels remained unchanged following EBV infection." (PMID 32273550, 2020). "In vivo, MAOA knockout inhibited tumor growth, metastasis, and the expression of EMT-related markers and HIF-1α proteins induced by HPV-16 E7 in NCI-H460 NSCLC subcutaneous xenograft and in situ intrapulmonary models of nude mice." (PMID 32792865, 2020). "Data showed significantly increased MAOB expression (Z score = 4.01) and slightly decreased MAOA expression (Z score = −1.18) in CRC tumor tissues." (PMID 32316576, 2020). "In this study, in vivo experiment showed that the tumor volumes were reduced and the MAOA expression level was significantly elevated in the NC‐treated group compared with the control group." (PMID 32931665, 2020). "Our data showed that tumor tissues had significantly lower MAOA expression (p < 0.0001) and higher MAOB expression (p = 0.0002) compared to the paired non-tumor counterparts." (PMID 32316576, 2020).